ENSG00000201733
Synonyms: LOC124900311
Gene: Small nucleolar RNA gene on chromosome 11 (66,432,763 to 66,432,902, forward strand). Ensembl gene ENSG00000201733.
Gene Ontology:
Biological process: RNA processing
Cellular component: nucleolus
Homologues: Paralogues in human: SNORA17B (74% identical), SNORA17A (55% identical).